BRMS1 (BRMS1 transcriptional repressor and anoikis regulator)
Diseases named in the same sentence as BRMS1 in open-access papers (continued):
Sharing a sentence is not in itself a finding about the gene and the disease.
breast carcinoma (continued). "The BRMS1 gene is located at 11q13.1-13.2, a region often altered in late-stage breast cancers, while in close proximity to the genomic loci that contains deletions and amplifications commonly observed in progression of breast cancer." (PMID 28533425, 2017). "By treating breast cancer cells with differential expression of the ER subtypes with E2, we observed that the regulation of E2 on the metastasis suppressor gene BRMS1 induced a time-dependent increase in the amount of BRMS1 protein produced only in ERα positive MCF-7 cells." (PMID 26821020, 2016). "In this study, we investigated whether expression of the breast cancer metastasis suppressor gene BRMS1 changed in response to estrogen exposure." (PMID 26821020, 2016). "Based on this information, we investigated whether BRMS1 expression in breast cancer cells was mediated through a specific estrogen receptor in response to estrogen." (PMID 26821020, 2016). "BRMS1 strongly inhibited TGF-β1-induced breast cancer cell EMT and invasion." (PMID 26520789, 2015). "Our results demonstrate that BRMS1 attenuates TGF-β1-induced breast cancer cell invasion through inhibition of NF-κB and subsequent reduction of HIF-1α expression required for Snail and TWIST1 expression, uncovers a new mechanism through which BRMS1 suppresses breast cancer progression." (PMID 26520789, 2015). "Given that BRMS1 has been known to attenuate cancer cell metastasis, we first determined whether BRMS1 inhibits TGF-β1-induced breast cancer cell invasion." (PMID 26520789, 2015). "Given that BRMS1 inhibits Snail and TWIST1 expression and that hypoxic condition induces Snail and TWIST1 expression in breast cancer cells, we hypothesized that BRMS1 inhibits HIF-1α expression." (PMID 26520789, 2015). "Indeed, ectopic expression of BRMS1 significantly inhibited TGF-β1-induced breast cancer cell invasion." (PMID 26520789, 2015). "Since EMT process is important for cancer cell invasion, we next determined whether BRMS1 regulates breast cancer cell EMT." (PMID 26520789, 2015). "Furthermore, miR-146 levels are significantly up-regulated by breast cancer metastasis-suppressor 1 (BRMS1), a gene that affects multiple steps in the metastatic cascade, which leads to a suppression of metastasis of ~90% in breast carcinomas." (PMID 25598707, 2014). "Through western blots of cytosolic and nuclear fractions of 901-tagged BRMS1-transfected MDA-MB-435 cells and micrographs of phase staining and immunofluorescence, another study confirmed the predominant nuclear localisation of BRMS1 in breast carcinoma cell lines." (PMID 24688598, 2014). "To identify whether there were any downstream targets transcriptionally regulated by the BRMS1 mutant proteins; we performed breast cancer disease specific arrays (DSATM, Almac Diagnostics, Durham, NC)." (PMID 23390556, 2013). "More importantly, the tumor suppressor role of BRMS1 is not only limited to breast carcinomas." (PMID 22927944, 2012). "Hurst and coworkers showed that breast cancer metastasis suppressor 1 (BRMS1), a protein that regulates expression of multiple genes leading to suppression of metastasis, significantly up-regulates miR-146a and miR-146b in metastatic breast cancer cells." (PMID 22408395, 2012). "Functional interaction research in breast cancer indicates that breast cancer metastasis suppressor 1 (BRMS1) up-regulates miR-146a and b; expression of either miRNA resulted in down-regulation of epidermal growth factor receptor (EGFR) and reduced invasion, migration, and metastasis." (PMID 23335942, 2012). "Breast cancer metastasis suppressor 1 (BRMS1) was originally identified following differential expression comparisons of chromosome 11 microcell hybrids in a human breast carcinoma cell line and was further mapped to chromosome fragment 11q13, a region frequently altered in melanomas." (PMID 22356677, 2012).
breast carcinoma (continued). "We examined whether fascin-mediated breast cancer cell invasion has an effect on the expression levels and cellular localization of BRMS1." (PMID 22076152, 2011). "BRMS1 has been reported to block lung and regional lymph node metastasis in experimental breast models and decreased expression of this protein has been demonstrated to correlate with reduced disease-free survival in human breast cancer." (PMID 22076152, 2011). "BRMS1 is a known metastasis suppressor in many cancer types including breast cancer." (PMID 22076152, 2011). "BRMS1 has been shown to suppress metastasis of breast cancer and melanoma in animal model studies." (PMID 17227585, 2007). "In addition, BRMS1 has been found to upregulate miR-146 and suppress breast cancer metastasis." (PMID 34054958, 2021). "Breast cancer metastasis suppressor 1 (BRMS1) is a member of a subclass of the metastasis suppressor family, and its repressive effects on distant metastasis have been observed in several human cancers including BC." (PMID 31901237, 2020). "Unexpectedly, we observed that BRMS1 downregulates not only TWIST1 but also Snail expression, thereby inhibiting breast cancer cell invasion." (PMID 26520789, 2015). "Strikingly, our present data show that BRMS1 downregulates not only TWIST1 but also Snail expression, thereby attenuating TGF-β1-induced breast cancer cell EMT and invasion." (PMID 26520789, 2015). "Taken together, these results show that BRMS1 mediates Cullin3-induced EMT, migration and invasion in breast cancer cells." (PMID 26544623, 2015). "For breast cancer, of the six predicted candidates (PRKCQ, ARAF, MAPK14, BRMS1, CDC42BPA, SP3), three (PRKCQ, ARAF, MAPK14) are members of at least one KEGG cancer relevant pathway." (PMID 25961669, 2015). "When BRMS1 was transfected into metastatic MDA-MB-231 and MDA-MB-435 breast cancer cells, the cell lines showed reduced metastasis." (PMID 23202960, 2012). "BRMS1 is a member of mSin3-HDAC transcription co-repressor complex and has been shown to suppress the metastasis of breast cancer and melanoma cells in animal models." (PMID 17227585, 2007). "Additionally, BRMS1 functions as a negative regulator of EGFR, indicating its potential to inhibit breast cancer progression." (PMID 40521202, 2025). "However, in breast cancer, SPOP appears to promote tumor metastasis by degrading BRMS1 76, a key metastasis suppressor gene." (PMID 40521202, 2025). "Hence, it is interest to document the molecular docking analysis of SR9009 (a pyrrolederivatives) with different breast cancer target protein targets such as HER2, Erα, PR, PI3K, AKT, Reverbα, BRMS1, Aromataseand mTOR, CDK4, CDK6, TK and Top II." (PMID 40230904, 2024). "Moreover, we reported that in breast cancer, CST6 and BRMS1 methylation was detected in ctDNA and CTCs, in ovarian cancer RASSFIA and ESR1 methylation was detected in ctDNA, while in NSCLC BRMS1 and SOX17 methylation was detected in ctDNA." (PMID 34572834, 2021). "However, in a previous study, JARID1C promoted metastasis of breast cancer cells via down regulation of BRMS1 expression, and silencing of JARID1C dramatically increased BRMS1 expression, both at the mRNA and protein level." (PMID 33042830, 2020). "Kaplan–Meier estimates of the cumulative Disease Free Interval (DFI) were significantly different in favor of patients with non-methylated BRMS1 promoter (Ρ = 0.042), as we have previously reported for a different cohort of breast cancer patients." (PMID 29069768, 2017). "Administration of a heterogeneity test discovered the lack of heterogeneity in the expression of BRMS1 protein between breast cancer tissues and normal tissues, requiring implementation of a random effect model (P = 0.219, I2 = 32.1%)." (PMID 28533425, 2017). "The intensity of the BRMS1 staining in CK-expressing cells was semi-quantitatively measured (negative/low/high), using the epithelial breast cancer MCF7 cell line and normal PBMCs as standards." (PMID 26506390, 2015).
breast carcinoma (continued). "A previous study has shown a dose-dependent significant decrease in the metastatic potential of BRMS1-transfected breast carcinoma cells in an animal model, while no change in tumourigenicity was observed." (PMID 24688598, 2014). "The role of BRMS1 is well-documented for several non-melanoma malignancies, such as breast cancer, ovarian cancer and non-small-cell lung cancer." (PMID 22356729, 2012). "BRMS1 reduces the metastatic potential, but not the tumorigenicity, of human breast cancer and melanoma cell lines." (PMID 20195375, 2010). "In addition to decreased protein expression, the BRMS1 expression in metastatic breast cancer tissue was lower than non-metastatic breast cancer tissue, suggesting invasion and metastasis of breast cancer might possibly be linked to the reduction or absence of BRMS1 expression." (PMID 28533425, 2017). "BRMS1 has been first described in 2000 following the observation thatentering a typical, neomycin-tagged human chromosome 11 decreased metastatic potential ofthe MDA-MB435 human breast cancer cells by 70- 90% with no prevention of primary tumorgrowth." (PMID 34096224, 2021). "The effect of BRMS1 on OPN expression shows that it plays a suppressive role in regulating the transcriptional activity of the OPN gene promoter in HCC cells as demonstrated by dual luciferase assay in vitro (data not shown), which is consistent with previous reports in breast cancer." (PMID 22927944, 2012).
melanoma (23 papers, 2007 to 2020). A malignant, usually aggressive tumor composed of atypical, neoplastic melanocytes. "In contrast, the melanoma samples used here show that cytoplasmic expression of BRMS1 is inversely associated with markers of proliferation, cyclin D3, cyclin A, Ki67, p21Waf1/Cip1." (PMID 22356677, 2012). "When examining the melanoma panel for a possible association between BRMS1 and FABP7, a significant correlation between nuclear BRMS1 expression (percentage of immunoreactive cells) and the level of FABP7 (p = 0.011) was observed." (PMID 22356677, 2012). "Loss of BRMS1 resulted in deficient suppression of vasculogenesis and contributed to melanoma metastasis." (PMID 22200669, 2012). "Nuclear BRMS1 expression in ≥ 10% of primary melanoma cells was associated with thicker tumors (p = 0.016) and decreased relapse-free period (p = 0.043)." (PMID 22356677, 2012). "The higher nuclear expression of BRMS1 found in benign nevi than in primary melanomas or metastases seems contradictory to the association to prolonged disease-free survival for patients having low nuclear tumor expression of BRMS1." (PMID 22356677, 2012). "To address this, we screened protein expression of five melanoma metastasis suppressors (BRMS1, gelsolin, GAS1, NME1/NM23-H1, and KAI1) following KDELR3 knockdown." (PMID 31949145, 2020). "Breast cancer metastasis suppressor 1 (BRMS1), a known metastasis suppressor gene, has been shown to suppress metastasis of a variety of tumor cell lines, including breast, melanoma, bladder, ovarian and lung." (PMID 26821020, 2016). "We conclude that the reduction of iASPP expression in melanoma facilitates BRMS1-mediated p300/CBP turnover, thereby contributing to chemoresistance." (PMID 25675294, 2015). "In line with our findings, iASPP overexpression or knockdown of BRMS1 each augmented p300/CBP levels in melanoma cell lines, thereby enhancing apoptosis upon DNA damage." (PMID 25675294, 2015). "In fact, a recent clinical study of malignant melanoma suggested that localization of BRMS1 in the cytoplasm inhibits tumor progression and nuclear BRMS1 actually promotes melanoma cell invasion." (PMID 23390556, 2013). "In line with this, repression of BRMS1 expression reduced the ability of melanoma cells to migrate and invade in vitro." (PMID 22356677, 2012). "In support of this, we showed that down-regulation of BRMS1 in two metastatic melanoma cell lines, expressing predominantly nuclear BRMS1, reduced the invasive ability." (PMID 22356677, 2012). "Since this panel of melanoma tissues has been previously analyzed for factors involved in cell proliferation, it was of interest to examine the relationship between BRMS1 expression and the levels of those factors." (PMID 22356677, 2012). "Another tumor suppressor gene, BrMS1, located at 11q13 is altered in many melanomas and breast cancers." (PMID 22481931, 2012). "Our previous studies found that 12 markers including pAkt, Bim, BRG1, BRMS1, CTHRC1, Cul1, ING4, MCL1, NQO1, SKP2, SNF5 and SOX4 were associated with melanoma progression." (PMID 23028750, 2012). "Their findings emphasize that the intracellular location of BRMS1 protein (cytoplasmic or nuclear), appears to have a significant impact upon the metastatic capacity of melanoma cells." (PMID 22356729, 2012). "Nuclear BRMS1 was associated with expression of fatty acid binding protein 7 (FABP7; p = 0.011), a marker of invasion in melanomas." (PMID 22356677, 2012). "In melanoma cell lines, BRMS1 was localized mainly in the nucleus, although some cytoplasmic expression was also seen." (PMID 22356677, 2012). "Subsequent studies have demonstrated that BRMS1 dramatically suppresses the metastatic phenotype in vitro in cells from several othertypes of cancer, including melanoma, ovarian cancer, bladder cancer and lung cancer." (PMID 22931099, 2012). "Paraffin-embedded tissue from 155 primary melanomas, 69 metastases and 15 nevi was examined for BRMS1 expression using immunohistochemistry." (PMID 22356677, 2012).
melanoma (continued). "A recent study has shown that the cell cycle regulator, ING4, is a suppressor of melanoma angiogenesis, regulated and induced by BRMS1 expression and further inhibiting NF-KB activity and IL-6 expression." (PMID 22356729, 2012). "Immunohistochemistry was applied to examine the level of BRMS1 protein in a panel of benign nevi and primary and metastatic melanomas in order to evaluate the impact of altered expression on clinical outcome." (PMID 22356677, 2012). "BRMS1 has since been shown to suppress metastasis in many other cancer types such as melanoma, ovarian carcinoma and non-small lung cancer, among others." (PMID 22927944, 2012). "From a treatment perspective, the importance of this study will be realized if bioactive agents can be developed that have the capacity to change both the (natural) balance and location of BRMS1 expression within melanoma cells." (PMID 22356729, 2012). "A significantly higher percentage of nevi (87%), compared to primary melanomas (20%) and metastases (48%), expressed BRMS1 in the nucelus (p < 0.0001)." (PMID 22356677, 2012). "siRNA mediated BRMS1 down-regulation was used to study impact on invasion and migration in melanoma cell lines." (PMID 22356677, 2012). "Protein expression of BRMS1 was analyzed by immunohistochemistry in a panel of paraffin-embedded benign nevi and primary and metastatic melanoma tissues as well as in two melanoma cell lines." (PMID 22356677, 2012). "In contrast to the results obtained in another melanoma cohort, as well as in breast and NSCL cancers our study showed that high nuclear expression of BRMS1 was associated with more aggressive tumors and shorter disease-free survival." (PMID 22356677, 2012). "Recent evidence strongly suggests that BRMS1 represents an important biomarker with prognostic significance, further serving as a therapeutic target for melanoma patients." (PMID 22356729, 2012). "miR-18a predicted target BRMS1, a nuclear metastasis suppressor gene, is found to suppress experimental metastasis of melanoma, bladder and ovarian carcinomas." (PMID 19898689, 2009). "Past studies alluded to reports that BRMS1 reduced lung metastasis in athymic mice when its expression was restored by exogenous expression of BRMS1 in metastatic cell lines from non-small cell lung carcinomas, ovarian, melanoma, and breast." (PMID 28533425, 2017). "Similarly, transient depletion of BRMS1 partially re-established p300/CBP levels in cisplatin-treated melanoma cell lines." (PMID 25675294, 2015). "BRMS1 has variations in 51 samples from 15 adult cancers (Acute myeloid leukaemia, Bladder, Breast, Cervical, Colorectal, Melanoma, Head & neck, Liver, Lung adenocarcinoma, Lung squamous cell carcinoma, Pancreas, Papillary renal cell carcinoma, Prostate, Stomach, Uterine cancer)." (PMID 26486520, 2015). "The authors hypothesised that cytoplasmic BRMS1 restricts melanoma progression while possibly nuclear BRMS1 promotes melanoma cell invasion." (PMID 24688598, 2014). "Together these results suggest that cytoplasmic BRMS1 may at least partly negatively regulate melanoma progression and metastasis through sequestering of activated ERK1/2 in the cytoplasm and by preventing accumulation of nuclear active Akt." (PMID 22356677, 2012). "Ultimately, the question can be asked as to whether the specific location of BRMS1 activity can make a difference in the destined outcome for melanoma patients." (PMID 22356729, 2012). "Similarly, melanoma cells re-expressing BRMS1 were less invasive and had restored intercellular communication." (PMID 22356677, 2012). "We hypothesize that cytoplasmic BRMS1 restricts melanoma progression while nuclear BRMS1 possibly promotes melanoma cell invasion." (PMID 22356677, 2012). "Moreover, BRMS1 has been shown to negatively regulate melanoma angiogenesis by suppressing NF-κB activity and IL-6 expression." (PMID 22200669, 2012).
melanoma (continued). "In addition, in a third study, BRMS1 mRNA levels were measured in a panel of skin melanocyte- and melanoma-derived cell lines representing a continuum of skin melanoma stages of progression and it was found that mRNA levels decreased as the cell lines’ metastatic potential increased." (PMID 24688598, 2014). "To examine in more detail whether BRMS1 affects migration and invasion of melanoma cells we transiently down-regulated BRMS1 expression using siRNA in two metastatic melanoma cell lines (WM239, FEMX-1) and performed a transwell chamber invasion/migration assay." (PMID 22356677, 2012). "Furthermore, CTHRC1 may be a useful marker for primary melanoma and BRMS1 serves an important marker for metastatic melanoma distinguishing from dysplastic nevi." (PMID 23028750, 2012). "Thus, many other questions emerge unanswered and will require further research to elucidate the importance of BRMS1 expression in melanoma, whether nuclear or cytoplasmic." (PMID 22356729, 2012). "Looking forward, if one was capable of restoring BRMS1 expression via reversal of epigenetic silencing, could we concomitantly regulate its intracellular location and activity in tumor cells to achieve the desired therapeutic outcome in melanoma patients." (PMID 22356729, 2012). "Furthermore, the CTHRC1 marker may be a useful marker for primary melanoma and BRMS1 serves an important marker for metastatic melanoma distinguishing form dysplastic nevi." (PMID 23028750, 2012). "Nonetheless, although recent literature suggest that BRMS1 may play roles during tumor progression other than the metastasis suppressor function originally suggested, this study was undertaken to investigate the importance of BRMS1 expression and subcellular localization on melanoma progression." (PMID 22356677, 2012). "Re-expression of BRMS1 in human breast, non-small cell lung (NSCL) and ovarian carcinomas and in melanoma cell lines resulted in marked reduction of metastasis without blocking orthotopic tumor growth." (PMID 22356677, 2012). "Immunohistochemical expressions of 12 promising biomarkers (pAkt, Bim, BRG1, BRMS1, CTHRC1, Cul1, ING4, MCL1, NQO1, SKP2, SNF5 and SOX4) were studied in 122 melanomas and 33 dysplastic nevi on tissue microarrays." (PMID 23028750, 2012). "Therefore, JAK3 may function together with BRMS1 and EDAR to suppress the migration and invasion of melanoma cells." (PMID 32051510, 2020).